MAGEB2 (MAGE family member B2)
Description:
May enhance ubiquitin ligase activity of RING-type zinc finger-containing E3 ubiquitin-protein ligases. Proposed to act through recruitment and/or stabilization of the Ubl-conjugating enzyme (E2) at the E3:substrate complex.
Synonyms: CT3.2; DAM6; MAGE-XP-2; MGC26438
Tractability: PROTAC: ubiquitination databases record sites on it.
Gene: Protein-coding gene on chromosome X (30,215,563 to 30,220,089, forward strand). Ensembl gene ENSG00000099399.
Subcellular location (Human Protein Atlas): Cytosol
Gene Ontology:
Molecular function: protein binding
Biological process: negative regulation of transcription by RNA polymerase II
Cellular component: nucleus; cytoplasm
Homologues: Orthologues: chimpanzee MAGEB2 (96% identical), dog MAGEB4 (63% identical), mouse Mageb4 (54% identical), mouse Gm62087 (51% identical), rat AABR07038553.1 (50% identical), rat Mageb1 (49% identical), rat Mageb7 (45% identical), zebrafish ndnl2 (21% identical), Drosophila melanogaster MAGE (21% identical). Paralogues in human: MAGEB4 (65% identical), MAGEB1 (65% identical), MAGEB18 (52% identical), MAGEB17 (51% identical), MAGEB3 (50% identical), MAGEB6B (49% identical), MAGEB10 (49% identical), MAGEB6 (47% identical), MAGEB16 (45% identical), MAGEA4 (42% identical), MAGEA10 (41% identical), MAGEA11 (40% identical), and 25 more.
Diseases named in the same sentence as MAGEB2 in open-access papers:
MAGEB2 is named in the same sentence as 23 diseases in open-access papers, as found by Europe PMC text mining. Sharing a sentence is not in itself a finding about the gene and the disease. The quoted sentences say what the papers report.
colon cancer (4 papers, 2022 to 2025). "There was a concomitant decrease in the methylation of the MAGEB2 promoter in colon cancer tissue when compared to normal colon mucosa or adenomatous polyp." (PMID 40141091, 2025). "We then analyzed the methylation status of MAGEB2 promoter in normal colon, adenomatous polyp, and colon cancer tissue." (PMID 40141091, 2025). "For example, it has been reported that MAGEB2 promotes the cell proliferation in transformed oral keratinocytes, osteosarcoma and colon cancer cell lines." (PMID 36428603, 2022). "MAGEB2 binds to histone deacetylase 1 (HDAC1) and activates the transcription factor E2F (E2F) that stimulates the proliferation of colon cancer cells." (PMID 37304127, 2023).
head and neck squamous cell carcinoma (3 papers, 2012 to 2022). A squamous cell carcinoma that arises from any of the following anatomic sites: lip and oral cavity, nasal cavity, paranasal sinuses, pharynx, larynx, and salivary glands. "Genome-wide analysis in head and neck squamous cell carcinoma revealed that MAGEB2 is activated by promoter demethylation and demonstrates a growth-promoting effect in a minimally transformed oral keratin-forming cell line." (PMID 36085146, 2022). "Melanoma-Associated Antigen B2 (MAGEB2) belongs to the melanoma antigen gene (MAGE-I) family of tumor-specific antigens and is associated with several tumor diseases, such as head and neck squamous cell carcinoma, laryngeal cancer and nerve sheath tumors." (PMID 36085146, 2022). "We identified MAGEB2 as having significant promoter demethylation in primary head and neck squamous cell carcinoma tissues." (PMID 23029077, 2012).
melanoma (3 papers, 2016 to 2025). A malignant, usually aggressive tumor composed of atypical, neoplastic melanocytes. "The results show that the two variant alleles of the rs1800522 AIRE SNP differently modulate MAGEB2-specific T cell survival and in vivo susceptibility to melanoma." (PMID 27563821, 2016). "Moreover, the extent of apoptosis induced by mTECs in MAGEB2-specific T cells and the susceptibility to in vivo melanoma B16F10 cell challenge were compared in the two mouse strains." (PMID 27563821, 2016). "The C allelic variant, protective in humans against melanoma, induced lower AIRE and MAGEB2 expression in C57BL/6 mouse mTECs than the T allele." (PMID 27563821, 2016). "Vaccination against MAGEB2 induced higher frequency of MAGEB2-specific CTL and exerted higher protective effect against melanoma development in mice bearing the CC AIRE genotype than in those bearing the TT one (p < 0.05)." (PMID 27563821, 2016). "MAGEB2 gene, expressed both by C57BL/6 mice and B16F10 melanoma cells (our observation), was selected as a reference antigen for measuring MA-specific T cell response because MAGE antigens are AIRE-dependent antigens expressed by mTECs and have been suggested to be tumor rejection antigens." (PMID 27563821, 2016). "Interestingly, a band corresponding to CpG island 2 of MAGEB2 gene was observed after PCR amplification of DNA from mTECs pre-treated with an AIRE-specific siRNA but not from untreated mTECs or B16F10 melanoma cells, which costitutively express MAGEB2." (PMID 27563821, 2016).
Autoimmunity (2 papers, 2017 to 2021). The occurrence of an immune reaction against the organism's own cells or tissues. "Together with established autoimmunity targets, they detected melanoma-associated antigen B2 (MAGEB2) and disulfide isomerase-like protein of the testis (PDILT) as gonadal self-antigens." (PMID 33717087, 2021).
breast carcinoma (2 papers, 2022 to 2023). "Overexpression of MAGEB2 significantly recovered the proliferation and migration abilities of breast cancer cell with ZNF276 silencing." (PMID 36085146, 2022). "MAGEB2 was reported to be related to the progression of squamous cell carcinoma and breast cancer." (PMID 37304127, 2023). "Targeting ZNF276/MAGEB2 axis may serve as a potential therapeutic strategy for breast cancer patients." (PMID 36085146, 2022). "ZNF276 recruits MAGEB2 to facilitate the transcription of CYP1B1 and the activation of the Wnt/β-catenin pathway, leading to a malignant breast cancer phenotype." (PMID 36085146, 2022).
Infertility (2 papers, 2016). "The gonadal-specific expression of MAGEB2 and PDILT raises the questions whether these antigens may have a role in infertility in APS1." (PMID 26830021, 2016). "The identification of MAGEB2 and PDILT reveals the gonadal germ cells as major immune targets in APS1, and discloses yet another autoimmune component that potentially could contribute to infertility in male and female patients with APS1." (PMID 26830021, 2016). "Moreover, two novel gonadal autoantigens, melanoma antigen family B 2 (MAGEB2) and protein disulfide isomerase-like testis (PDILT), have been identified that potentially could contribute to infertility in male and female patients with APECED." (PMID 27597936, 2016).
laryngeal carcinoma (2 papers, 2022). Carcinoma that arises from the laryngeal epithelium. "Despite the limitations of our study (small number of patients), the most interesting finding is that the MAGEB2 expression was revealed to be the only gene able to distinguish resistant versus sensitive laryngeal cancer patients to conventional treatment." (PMID 36428603, 2022). "Further evidence for the involvement of MAGEB2 in modulating resistance comes from the fact that its inhibition in resistant laryngeal cancer cells (JHU029-R) sensitises these cells to the effects of CDDP." (PMID 36428603, 2022).
ovarian carcinoma (2 papers, 2014 to 2022). A malignant neoplasm originating from the surface ovarian epithelium. "Treatment of the ovarian cancer cell line A2780, for 72 hours with 500 nM carboplatin does not lead to overexpression of AIM genes IFI27, IRF7, IL15, or MAGEB2, all of which are increased in AZA-treated cells." (PMID 24583822, 2014).
myeloma (1 paper, 2015). "Among the genes located on chromosome X, CTAG1, CTAG2 and MAGEB2 belong to the cancer testis gene family (CTAGs), which have been previously demonstrated to have prognostic value in patients with myeloma." (PMID 24913504, 2015).
Premature ovarian insufficiency (1 paper, 2016). Amenorrhea due to loss of ovarian function before the age of 40. "In total MAGEB2 autoantibodies were detected in 31 out of 92 (34%) patients with APS1, in a single male with idiopathic infertility, just above cutoff in a female with premature ovarian insufficiency and were absent in all healthy controls." (PMID 26830021, 2016).
sarcomatoid mesothelioma (1 paper, 2024). A diffuse malignant mesothelioma arising from the pleura and less often the peritoneum. "Conversely, several genes reported to be expressed in sarcomatoid mesothelioma were preferentially expressed in cluster 1: members of the MAGE family MAGEA1, MAGEA3, MAGEB2 and MAGEA6." (PMID 38212075, 2024).
tumor (14 papers, 2012 to 2024). "Interestingly, the high MAGEB2 expression was associated with resistant tumours and is revealed as a novel target to sensitise resistant cells to therapy in HNSCC patients." (PMID 36428603, 2022). "Interestingly, the MAGEB2 expression has been associated with the inflammatory response in tumour laryngeal tissue." (PMID 36428603, 2022). "Since only MAGEB2 showed near statistical significance for promoter demethylation in tumors we proceeded to assess if promoter demethylation of MAGEB2 is associated with tumor specific increased MAGEB2 gene expression." (PMID 23029077, 2012). "One network comprises well known cancer antigens (e.g. GAGE1, MAGEB2, MAGEC2 and SSX1) associated with short overall survival and additional aggressive tumour properties." (PMID 36649303, 2023). "The observed oncogenic effect of MAGEB2 promoting resistance correlates with other described aspects of MAGEB2 promoting the cell proliferation in tumour cells." (PMID 36428603, 2022). "Overall, the overexpression of MAGEB2 was identified in resistant tumours, revealing it as a novel protein targeting sensitised HNSCC resistant patients." (PMID 36428603, 2022). "Here, we propose a novel function of MAGEB2 related to the CDDP resistance in HNSCC tumours, expanding its potential oncogenic role in cancer resistance." (PMID 36428603, 2022). "Only for MAGEB2 there was a trend of significant promoter demethylation in HNSCC tumor samples compared to normal mucosa samples (non parametric Wilcoxon test p = 0.08)." (PMID 23029077, 2012). "Furthermore, MAGEB2 can improve the stress tolerance of tumor cells by inhibiting the synthesis of stress granules; PAGE1 is also highly expressed in HCC cells and is considered as a potential biomarker and therapeutic target." (PMID 36173462, 2023). "We assayed bisulfite extracted DNA from 76 HNSCC tumor tissues and 17 normal mucosa samples for MAGEB2, KBGP/XK, DEAD/DDX43 which were found according to the preliminary BSS to be the most highly significant and showed high upfold expression values in AZA treated OKF6-T1 cell line." (PMID 23029077, 2012). "Since we found that MAGEB2 was overexpressed almost exclusively in tumors as a result of promoter demethylation we further sought whether it may have a role as an oncogene promoting tumor growth and development." (PMID 23029077, 2012). "First, we found multiple MAGE family proteins (e.g., MAGEC2, MAGEB2, MAGEC1, MAGEB6) with a gene expression profile similar to those in clinical trials (MAGEA1, MAGEA4), which have been reported to be tumor specific." (PMID 39515334, 2024). "Normal and tumour tissues from such patients were analysed by qRT-PCR for the following 12 genes; six from RNA-seq: CLDN1, MAGEB2, CD24, CEACAM6, IL1B and ISG15 and six from RNA-seq and proteomics cross-linking: AKR1C3, TNFAIP2, RAB7A, LGALS3BP, PSCA and SSRP1." (PMID 36428603, 2022). "This is in accordance with our findings of heterogeneous MAGEB2 expression, in HNSCC tumor tissues." (PMID 23029077, 2012). "Our analysis identified high expression of MAGEB2, MAGEC3, and MAGEB17 only in the non-viral-infected tumor group, in which we observed the overexpression of genes involved in stress response." (PMID 36557005, 2022).
cancer (12 papers, 2011 to 2025). A tumor composed of atypical neoplastic, often pleomorphic cells that invade other tissues. "To determine which signaling pathways are altered upon expressing MAGEB2, we performed an RT-qPCR array for cancer-associated genes." (PMID 40141091, 2025). "The association of the MAGEB2 expression with the CDDP response suggests its important clinical potential as a target for cancer therapy." (PMID 36428603, 2022). "MAGEB2 has been reported to be overexpression in several types of carcinomas, which has been implicated in carcinogenesis and identified as a potential cancer biomarker." (PMID 36085146, 2022). "To determine whether the aberrant re-expression of MAGEB2 in cancer has functional consequences, or whether it is caused due to the generalized and rampant de-regulated expression of many genes, we performed gain- and loss-of-function studies." (PMID 40141091, 2025). "Our data show that MAGEB2 is a true cancer-testis antigen and is expressed by the epigenetic regulation of its promoter region, specifically, CpG methylation." (PMID 40141091, 2025). "The depletion of MAGEB2 with siRNAs for 72 h results in a >50% decrease in the cell viability of patient-derived HCT116 cancer cells." (PMID 40141091, 2025). "Recently, MAGEB2 has been reported to be an RNA-binding protein that increases the stress tolerance of spermatogonial cells and cancer cells." (PMID 40141091, 2025). "Two protein-protein interaction networks were observed for genes upregulated in solid cancer: one network included products of cancer-specific genes such as MAGEB2, MAGEC2 and SSX1 for the whole cohort." (PMID 36649303, 2023). "This is in line with our hypothesis and data that MAGEB2 is expressed during the early onset of cancer via epigenetic mechanisms such as CpG methylation for the express purpose of conferring survival to cells." (PMID 40141091, 2025). "Moreover, MAGEB2 plays a role in enhancing the ribosome biogenesis as part of its repertoire to support cancer cell proliferation and is epigenetically activated in HNSCC." (PMID 36428603, 2022). "Given this and the fact that the cancer cell lines exhibited heterogeneity in the expression of MAGEB2, we sought to determine whether DNA methylation played a role in the expression of MAGEB2." (PMID 40141091, 2025). "Nucleolar MAGEB2 could also recruit phospho-upstream binding factor (pUBF) to the promoter of rDNA to activate rDNA transcription, accelerate ribosome biosynthesis and promote cancer cell proliferation." (PMID 36085146, 2022). "Of 90 CTAs validated by RNA sequencing, eight CTAs (DPEP3, EZHIP, MAGEA4, MAGEB2, MAGEC2, PAGE1, PRAME, and TKTL1) were selected for immunohistochemical profiling in cancer tissues from 328 NSCLC patients." (PMID 37341056, 2023). "Taken together, these data indicate that MAGEB2 is not expressed in any normal tissue or cell lines, but is highly, and variably, expressed in cancer cells and, therefore, is a true cancer-testis antigen." (PMID 40141091, 2025). "Our analysis of the data confirms that MAGEB2 is highly expressed in the testis and variably expressed in pan-cancer tissues, and we saw none-to-minimal expression in the heart tissues." (PMID 40141091, 2025). "We used MAGEA12 as an additional “negative” control because MAGEA12 is a cancer-testis antigen and the expression of MAGEA12 causes increases in cell proliferation; furthermore, MAGEA12 shares only 39% sequence identity with MAGEB2." (PMID 40141091, 2025).
MAGEB2 also shares sentences with these, for which no sentence is quoted: lung carcinoma (2 papers); conjunctival melanomas (1); embryonic tumors (1); glioblastoma (1); malignant peripheral nerve sheath tumor (1); nerve sheath tumors (1); neuroblastoma (1); osteosarcoma (1); spermatogenic failure (1); squamous cell carcinoma (1).